SNRNP27 (small nuclear ribonucleoprotein U4/U6.U5 subunit 27)
Description:
May play a role in mRNA splicing.
Synonyms: U4/U6.U5-27K; 27K; RY1
Tractability: Small molecule: a structure with a bound ligand is known. PROTAC: ubiquitination databases record sites on it; its protein half-life has been measured.
Gene: Protein-coding gene on chromosome 2 (69,893,956 to 69,905,929, forward strand). Ensembl gene ENSG00000124380.
Subcellular location: Nucleus
Subcellular location (Human Protein Atlas): Nucleoplasm
Pathways (Reactome):
Metabolism of RNA: mRNA Splicing - Major Pathway
Gene Ontology:
Molecular function: protein binding; nucleic acid binding
Biological process: mRNA splicing, via spliceosome; spliceosomal snRNP assembly; RNA splicing
Cellular component: precatalytic spliceosome; spliceosomal complex; U4/U6 x U5 tri-snRNP complex; nucleoplasm; nucleus
Genetic constraint (gnomAD): Loss-of-function variants: 10 observed, 9.37 expected, observed/expected ratio (o/e) 1.07, 90% interval 0.65 to 1.73. That is too few expected variants to judge how well the gene tolerates losing a copy. Missense variants: 65 observed, 106.15 expected, observed/expected ratio (o/e) 0.61, 90% interval 0.5 to 0.75. Synonymous variants: 33 observed, 33.63 expected, observed/expected ratio (o/e) 0.98, 90% interval 0.74 to 1.31.
Homologues: Orthologues: guinea pig SNRNP27 (100% identical), macaque SNRNP27 (100% identical), pig SNRNP27 (99% identical), mouse Snrnp27 (98% identical), rat Snrnp27 (91% identical), tropical clawed frog snrnp27 (86% identical), rat LOC100910341 (85% identical), dog SNRNP27 (81% identical), zebrafish snrnp27 (79% identical), Caenorhabditis elegans snrp-27 (50% identical).
Diseases named in the same sentence as SNRNP27 in open-access papers:
SNRNP27 is named in the same sentence as 1 disease in open-access papers, as found by Europe PMC text mining. Sharing a sentence is not in itself a finding about the gene and the disease.
SNRNP27 shares sentences with these, for which no sentence is quoted: Respiratory insufficiency (1 paper).